DCX (doublecortin)
Description:
Microtubule-associated protein required for initial steps of neuronal dispersion and cortex lamination during cerebral cortex development. May act by competing with the putative neuronal protein kinase DCLK1 in binding to a target protein. May in that way participate in a signaling pathway that is crucial for neuronal interaction before and during migration, possibly as part of a calcium ion-dependent signal transduction pathway. May be part with PAFAH1B1/LIS-1 of overlapping, but distinct, signaling pathways that promote neuronal migration.
Synonyms: DBCN; LISX; SCLH; DC; XLIS
Tractability: Small molecule: a structure with a bound ligand is known. PROTAC: UniProt records ubiquitination sites on it; its protein half-life has been measured.
Gene: Protein-coding gene on chromosome X (111,293,779 to 111,412,429, reverse strand). Ensembl gene ENSG00000077279.
Subcellular location: Cytoplasm; Cell projection, neuron projection
Subcellular location (Human Protein Atlas): Cytosol
Pathways (Reactome):
Developmental Biology: Neurofascin interactions
Gene Ontology:
Molecular function: microtubule binding; protein binding; protein kinase binding
Biological process: neuron migration; central nervous system development; nervous system development; axoneme assembly; intracellular signal transduction; retina development in camera-type eye
Cellular component: cytosol; neuron projection; cytoskeleton; microtubule associated complex; cytoplasm
Gene-disease validity (ClinGen):
ClinGen rates the evidence that DCX causes each of these diseases.
lissencephaly spectrum disorders (X-linked): Definitive.
Homologues: Orthologues: guinea pig DCX (99% identical), mouse Dcx (99% identical), rat Dcx (99% identical), pig DCX (99% identical), rabbit DCX (98% identical), chimpanzee DCX (94% identical), dog DCX (94% identical), macaque DCX (94% identical), tropical clawed frog dcx (89% identical), Caenorhabditis elegans mak-2 (13% identical). Paralogues in human: MKNK1 (17% identical), MKNK2 (17% identical), CAMK4 (16% identical), MAPKAPK3 (14% identical), MAPKAPK2 (14% identical), MAPKAPK5 (13% identical).
Diseases named in the same sentence as DCX in open-access papers:
DCX is named in the same sentence as 153 diseases in open-access papers, as found by Europe PMC text mining. Sharing a sentence is not in itself a finding about the gene and the disease. The quoted sentences say what the papers report.
Stroke (83 papers, 2011 to 2026). Sudden impairment of blood flow to a part of the brain due to occlusion or rupture of an artery to the brain. "Consistent with the neuroprotective role of NSCs, targeted depletion of both DCX- or Nestin-expressing cells in the SVZ has been linked to worsened stroke lesion size and motor impairment." (PMID 26696816, 2015). "Another possible alternative to explain the increase in DCX IR and NeuN IR after GH treatment during HI injury, could be linked to the role of this hormone upon proliferation and generation of neural cells in a stroke model." (PMID 36012320, 2022). "DCX staining was hardly detectable in the striatum of WT mice 2 weeks after pMCAO, suggesting that there was a strong decrease in stroke-induced neurogenesis in aged mice." (PMID 39596503, 2024). "Surprisingly, 2 months after the stroke, the DCX staining of sagittal sections of the Tlx-OE mice with stroke demonstrated that the majority of DCX-positive cells were still migrating to the lesion through the corpus callosum." (PMID 39596503, 2024). "In accordance with existing literature, stroke induced a significant increase in DCX+ cells in the ipsilateral, stroke-damaged striatum in all three groups." (PMID 38424560, 2024). "A dramatic increase in DCX-expressing cells was found on the stroke side of Tlx-OE mice 2 weeks after the stroke experiment." (PMID 39596503, 2024). "Brain sections were co-stained for BrdU/SOX2 (the recognized phenotypic marker for NSCs) and BrdU/DCX (the neuroblast marker) in the SVZ at 35 days after stroke to identify the proliferating and migrating cells, respectively." (PMID 39697542, 2024). "Despite varying results in the immunofluorescence analyses, IC, IA, and IN cell-treated stroke animals all displayed co-localization of CD34 with DCX and Iba-1, and CD34 was observed to be neighboring VEGFr1 markers in positive cells." (PMID 38016184, 2024). "Many DCX-expressing cells were found in Tlx-OE mice, which indicates that Tlx overexpression also strongly stimulated stroke-induced neurogenesis in aged animals." (PMID 39596503, 2024). "The altered development of the DCX+ precursors after stroke found here is similar to the one found in an epilepsy model, which is reinforced by the running task and contributes to increased aberrant neurogenesis." (PMID 36831319, 2023). "To determine the contribution of neurogenesis in post-stroke recovery we examined DCX, a marker for immature neurons in the sub-ventricular zone (SVZ)." (PMID 37817190, 2023). "Usingthis mouse line and consistent with our previous observations, migrations of DCX+ andtdTomato+ cells penetrated into the lesioned striatum at 30 daysafter stroke." (PMID 35905716, 2022). "In IF staining, protein levels of Nestin, Ki67, and DCX‐positive cells were significantly increased in the SGZ neurogenic niche of rats receiving three injections of CM compared with the untreated stroke rats (p < 0.05, p < 0.01, and p < 0.01, respectively)." (PMID 35715988, 2022). "In the comparison between single and multiple NPC-CM injections, NPC(M) resulted in substantially more NPCs (DCX+ cells) surrounding the SVZ in the stroke-affected hemisphere." (PMID 35887140, 2022). "Coronal slices from brains 6 days after PT stroke were co-stained for DCX and BrdU to determine if cTBS increased the number of immature neurons in the peri-infarct area." (PMID 35966576, 2022). "Data showed that the number of Dil‐labeled NSCs expressed DCX was increased in all groups compared to the Stroke + PBS group." (PMID 35111956, 2022). "Our studyprovides evidence that post-stroke treatment with a PTPσ selective inhibitorenhanced the total number and migration of DCX+ neuroblasts well into theglial-scarred infarct area." (PMID 35905716, 2022). "This lack of a contralateral effect is consistentwith the results that 30 days of ISP treatment in non-stroke mice does notchange total DCX+ or tdTomato cells in the SVZ." (PMID 35905716, 2022).
Stroke (continued). "The cTBS group, however, exhibited a markedly higher amount of DCX+ clusters than PT stroke only group." (PMID 35966576, 2022). "There were nodifferences in the total number of Ki67+ cells along the SVZ at 14days post-stroke and there were similar numbers of DCX+ andtdTomato+ cells within the same regions." (PMID 35905716, 2022). "After stroke, the transfer to an EE results in migration of neural DCX+ progenitor cells in the striatum in the peri-infarct region." (PMID 34447293, 2021). "Despite these extensive studies, several questions remain open, such as which DCX+ cells contribute to post-lesional neurogenesis and which stroke-induced factors trigger the altered migration of neuroblasts into the infarct area." (PMID 34447293, 2021). "After stroke, a transient increase in DCX+ neuroblasts, as well as long chains of migrating neuroblast associated with striatal blood vessels were detected." (PMID 34447293, 2021). "The extent to which these star shaped DCX+ glial cells can form mature neurons post-stroke is still unclear." (PMID 34447293, 2021). "Under pathophysiological conditions, such as stroke, the expression pattern of DCX changes and DCX+ cells can be detected in cortical and striatal areas outside the circumscribed neurogenic regions." (PMID 34447293, 2021). "Post-stroke blockade of α2β1 integrin had a greater inhibitory effect on DV-driven neurogenesis on DCX-positive cells in the peri-infarct region versus the peri-ventricular region." (PMID 32253702, 2021). "DCX immunofluorescence was significantly increased with DV treatment in the stroke-affected region on PSD 21 compared with vehicle-treated mice (p < 0.01)." (PMID 32253702, 2021). "Such questions include to what extent neuroblasts in the human brain can migrate from the neurogenic niche of the SVZ into the striatum or distant cortex and to what extent DCX+ neuroblasts contribute to functional recovery after stroke." (PMID 34447293, 2021). "We used the MCAO rat model and treated them with intravenous injections of sovateltide and examined the expression of DCX in brain tissues to assess the effect of stroke on neuronal cell population in the brain at 24 h post MCAO." (PMID 32728189, 2020). "Here, we showed that GH treatment in stroke mice also resulted in a significant increase in DCX-positive structures and protein levels within the peri-infarct region." (PMID 31963456, 2020). "We also found a significant increase in DCX protein levels (0.25-fold, p = 0.001) in r-hGH–treated stroke mice." (PMID 32604953, 2020). "Our results show an increased number of BrdU-positive cells and expression of DCX in the DG subregion in GH-treated stroke mice." (PMID 32604953, 2020). "Transgenic ablation of DCX resulted in exacerbation of stroke outcome and attenuation motor function recovery." (PMID 32281225, 2020). "After photothrombotic stroke, a lateralization of DCX+ neuroblasts towards the ischemic hemisphere was observed during the entire period of observation, both after OPN treatment as well as after PBS injection." (PMID 29973246, 2018). "Despite the presence of more DCX+ cells in N3H-fed aged mice, dietary supplementation did not lead to any significant differences in the number of post-stroke (BrdU+) DCX cells between N3L and N3H mice at 56 days after cerebral ischemia." (PMID 28966799, 2017). "In contrast, transgenic conditional ablation of DCX worsens stroke outcome both in the short and long term on a consistent basis." (PMID 25881110, 2015). "Our previous findings demonstrating that recovery following stroke correlates with the DCX expression in the PZ suggest a considerable role of DCX in the reorganization of the ischemic brain." (PMID 25881110, 2015). "Following stroke, DCX was found to be highly expressed in the perilesional cortex of focal ischemic infarcts - beyond the circumscribed neurogenic regions." (PMID 25881110, 2015).
Stroke (continued). "After stroke, neuroblasts—expressing doublecortin (Dcx)—are capable of travelling from the SGZ and SVZ towards the infarct." (PMID 25821957, 2015). "Immunofluorescence double labeling of DCX and the proliferation marker BrdU was performed at 6 days after stroke." (PMID 24503654, 2014). "The number of DCX+/BrdU+ cells was significantly greater in stroke mice that received PTH treatment (n = 7) than in stroke-saline mice (n = 6)." (PMID 24503654, 2014). "It has been known for some time that there is increased neurogenesis after injury in the neurogenic niches of the SVZ and SGZ (subgranular zone) of the dendate gyrus and that DCX+ cells migrate toward the lesion area after stroke or TBI." (PMID 24670035, 2014). "Future studies will need to differentiate between cell repair and true neurogenesis by examining earlier time points and quantifying DCX-positive neuroblasts migrating to the stroke region after treatment." (PMID 23928330, 2013). "In that case, part of the ectopic DCX pool induced by the stroke originated from the SVZ and migrated along vessels." (PMID 22038821, 2011). "However, there was a significant increase in the numbers of YFP+ cells that differentiated into DCX+ neuroblasts in the stroke+NWL283 group compared to stroke+vehicle (stroke+vehicle = 3.78 ± 2.22% vs. stroke+NWL283 = 16.03 ± 4.42%) (p = 0.038)." (PMID 38339065, 2024). "We have shown in previous studies that the DPP-4 inhibitor Linagliptin enhances the number of stroke-induced DCX+ neuroblasts in association with improved stroke recovery, even though T2D per se did not affect this cellular process." (PMID 38424560, 2024). "In the early phase of stroke, both HF-rTMS and iTBS increased the number of Ki67 and DCX/Nestin or NeuN+ cells suggesting that they could promote an increase in the neural stem cells (NSC) followed by a migration to the peri-infarct striatum." (PMID 36895285, 2023). "However, there was a significant decrease in the number of DCX+ precursor cells after standard housing in both the sham and stroke groups." (PMID 36831319, 2023). "Moreover, aerobic exercise has been demonstrated to ameliorate neurogenesis indicated by increased expression of BDNF and DCX positive cells in the ischemic hippocampus after stroke in rats." (PMID 36203743, 2022). "In the current study, Paeoniflorin administration promotes von Willebrand factor (an endothelia cell marker) and doublecortin (a neuroblasts marker) expression compared with control, suggesting that Paeoniflorin facilitates neurogenesis and vasculogenesis in rat stroke model." (PMID 34123580, 2021). "Compared with control, Paeoniflorin administration facilitated von Willebrand factor (an endothelia cell marker) and doublecortin (a neuroblasts marker) expression, indicating that Paeoniflorin contributed to neurogenesis and vasculogenesis in rat stroke model." (PMID 34123580, 2021). "Finally, physical exercise rapidly increased the amount of endogenous ANG in the ipsilateral SVZ niche after ischemia, where DCX-migrating cells increased as part of the post-stroke neurogenesis process." (PMID 34234733, 2021). "Interestingly, both the volume of the GCL, as well as the number of post-stroke DCX+ GCs correlated negatively with cognitive outcome, suggesting a deleterious effect on memory function through the abrupt addition of post-ischemic abGC." (PMID 34447293, 2021). "Two weeks after stroke, immature, DCX+ GCs showed an accelerated maturation of passive properties such as a lower input resistance, resting potential and membrane time constant, and were more likely to fire fast, brief action potentials characteristic of mature neurons." (PMID 34447293, 2021). "Transgenic ablation of SVZ-derived DCX-positive neuroblasts 14 days prior to stroke induction in adult mice increased infarct size and worsened neurobehavioral disabilities 24 h after stroke, suggesting that enhanced SVZ-neurogenesis is a first-line repair response." (PMID 32982671, 2020).
Stroke (continued). "Moreover, it was reported that DCX expression in the lesioned brain area following stroke correlates with the recovery of functional deficits." (PMID 32281225, 2020). "In our study, EA could promote neurogenesis after stroke and increase the number of DCX+/NeuroD1+ colocalization in the SVZ." (PMID 32792909, 2020). "However, the HT diet only induced Bdnf expression in stroke HT-mice, suggesting a difference in the response between Bdnf and DCX." (PMID 31614692, 2019). "Indeed, co-staining with the proliferation marker bromodeoxyuridine (BrdU) revealed an increased expression of both the immature neuronal marker doublecortin (DCX) and the mature neuronal marker NeuN in adolescent mice at four weeks after stroke induction." (PMID 31888056, 2019). "The DCX-luc mouse has recently been used to visualize endogenous neurogenesis after experimental stroke induced by transiently occluding the middle cerebral artery, a stroke model that leads to more extensive ischemic lesions than the ones induced by photothrombosis as used in our study." (PMID 29973246, 2018). "Since the underlying mechanism may involve neurogenesis, we investigated the immunoreactivity of the early neuronal marker doublecortin by immunofluorescence in the lateral ventricle region of aged rats after stroke." (PMID 27013593, 2016). "Also, in response to stroke, DCX positive cells deviate from the SVZ to the striatum, where they keep on dividing." (PMID 25719447, 2015). "Moreover, aLA treatment increased BrdU/DCX co-labeled cells, a marker for early neurogenesis, in the boundary zone at 2 weeks after stroke." (PMID 25761600, 2015). "Appearance of DCX-positive cells at ectopic sites also occurs in brain parenchyma following stroke." (PMID 22038821, 2011). "Indeed, when we compared the day 14 and day 30 stroke brains, weobserved further migration of tdTomato+ and DCX+ cellstoward the infarct area at day 30 compared to day 14, with increasedDCX+ cells navigating more deeply into the striatum inISP-treated mice (white arrows in B, and K)." (PMID 35905716, 2022). "DCX is mainly known to be expressed in the highly committed neuronal progenitors with very low multipotency and thus its expression level could represent the overall status of NPCs in brain after stroke and treatment." (PMID 32728189, 2020). "Interestingly, previous studies have demonstrated that the number of DCX-positive cells positively correlates with recovery from functional deficits after stroke and, on the other hand, conditional ablation of DCX deteriorates both short- and long-term functional outcomes post-stroke." (PMID 31963456, 2020). "Given that DCX is a marker of immature neuroblasts, we next determined whether n-3 PUFAs could stimulate the maturation of neural progenitor cells, which may be a stronger marker for neuronal remodeling after stroke." (PMID 28966799, 2017). "Notably, the number of DCX+ cells positively correlates with the recovery of functional deficits after stroke though the nature and origin of these cells remains unclear." (PMID 25881110, 2015). "Studies have shown that following BrdU or GFP lentiviral injections into the SVZ at the time of stroke, labeled cells are detected in peri-infarct cortex at 7 and 14 days post stroke, whereas injections of BrdU directly into the cortex results in only a few BrdU+/DCX+ cells." (PMID 26696816, 2015). "We also found that CAT significantly increased the number of BrdU+/DCX+ cells, suggesting that CAT promotes the differentiation of nascent NSCs into early neuronal cells during stroke recovery." (PMID 39749196, 2024). "At day 10 post-stroke, co-localizations of GFP and neural progenitor markers (DCX, PSA-NCAM) were observed in peri-infarct striatum in microvesicle-treated mice." (PMID 36535938, 2022).